GPC3 (glypican 3)
Diseases named in the same sentence as GPC3 in open-access papers (continued):
Sharing a sentence is not in itself a finding about the gene and the disease.
tumor (continued). "Preclinical studies have demonstrated that GPC3-targeting ADCs can effectively bind to HCC cells, induce internalization, and deliver cytotoxic payloads, resulting in significant anti-tumor activity in vitro and in vivo." (PMID 40621467, 2025). "Alternatively, immunotoxins, like our J80A-PE24, which is derived from anti-GPC3 antibody fragments conjugated to PE24, possess high specificity and low toxicity, yet are accompanied by their insufficient standalone anti-tumor effect." (PMID 40406146, 2025). "In antitumor immunity, the same cell subsets recognize tumor antigens, for example, AFP and GPC3, via the T cell receptor (TCR) and exert specific cytotoxicity against HCC cells." (PMID 41375072, 2025). "Specifically, ALB and CYP2E1 were highly expressed in normal areas, GPC3 and AKR1B10 were highly expressed in tumor areas, ACTA2 and COL1A1 were highly expressed in fibrostic areas, and PTPRC was highly expressed in inflammation areas." (PMID 40051627, 2025). "In preclinical studies, 32A9 inhibited tumor formation in mice and was effective in combination with CAR-T cells and immunotoxins, selectively killing GPC3-positive tumor cells." (PMID 40416124, 2025). "This suggests that GPC‐3 may undergo substantial translational and posttranslational regulation, such as phosphorylation or ubiquitination, potentially exerting a greater influence on tumor progression through protein‐level regulation compared to transcriptional changes." (PMID 39556692, 2025). "Histopathological confirmation was obtained via liver biopsy or surgical specimen, with immunohistochemistry performed to assess tumor differentiation using markers such as CK7, CK19, CK20, CK AE1/AE3, glypican-3, TTF-1, and CD34." (PMID 40843884, 2025). "Experimental studies in H22 tumor-bearing models and orthotopic HCC models revealed that this nanosystem leverages enhanced glypican-3 (GPC3) and tumor vascular cell adhesion molecule-1 (VCAM1) targeting to recognize and capture CTCs." (PMID 40528159, 2025). "Together, these findings underscore the theranostic potential of GPC3-targeted α-therapy in HCC, combining sensitive tumor imaging with potent tumoricidal alpha irradiation." (PMID 40722645, 2025). "Additionally, Glypican 3 (GPC3) is upregulated in tumors expressing specific PIK3CA mutations, and its overexpression induces aberrant synapse formation, exacerbating network hyperexcitability and accelerating the onset of seizures within the tumor microenvironment." (PMID 40076738, 2025). "The pathological specimens were analyzed for programmed death ligand 1 (PD-L1), Glypican-3, CD3-tumour infiltrating lymphocyte, CD68 positive cells, CD34 positive microvessel density (MVD)." (PMID 40640280, 2025). "Distinguishing YST from other tumor types can be challenging; however, IHC markers, such as sal-like protein 4 (SALL4) and glypican-3 (GLP3), are useful for accurate identification." (PMID 40370888, 2025). "Analysis of TCGA-LIHC data revealed elevated expression of SOX9, DCN, GPC3, and B3GNT3 in tumor tissues versus non-tumor counterparts." (PMID 41268541, 2025). "The strong GPC3 IHC staining in HepG2 xenografts supports the observed T1 signal enhancement in ET58-DOTA-Gd–injected mice, indicating effective and specific tumor targeting." (PMID 41154412, 2025). "Volcano plots were utilized to visualize the expression patterns of these genes, revealing that genes such as GPC3 and SPINK1 were significantly upregulated in the tumor group, while genes including HAMP and CYP1A2 were markedly downregulated." (PMID 40864066, 2025). "These architectural changes facilitate the upregulation of oncogenic drivers such as SOX4 and GPC3, with SOX4 promoting tumor neovascularization and metastasis, while GPC3 activates Wnt signaling to drive HCC growth." (PMID 40057667, 2025). "Immunohistochemically, the tumor showed strong positivity for CK19, CK7, and CD34 in ductular–trabecular structures, as well as glypican-3 and TTF-1 in solid components." (PMID 40843884, 2025).
tumor (continued). "The lower positive rates of AFP, GPC3, GS, and CD34 in the TRG1a group further indicate a lower residual tumor burden and a more favorable tumor biology responded to conversion therapy." (PMID 41246344, 2025). "Tumor cells exhibited a yolk sac tumor profile that included strong reactivity with SALL-4 and focal/weak reactivity with AFP and glypican-3." (PMID 41510478, 2025). "Among these, GPC3 and PLVAP were consistently upregulated, implicating their roles in tumor progression and angiogenesis across ethnicities." (PMID 41216224, 2025). "In vivo systemic administration of GPC3 Cas9‐RNP@UPSND resulted in preferential accumulation within hepatic tissues in orthotopic HCC mouse models, leading to complete tumor eradication and enhancing T‐cell tumor‐infiltration." (PMID 40657181, 2025). "In HCC, BsAbs are designed to target overexpressed TAAs, such as Glypican-3 and alpha-fetoprotein (AFP), to achieve tumor-specific recognition." (PMID 40918452, 2025). "Regarding gene amplification, EWSR1, FLT3, GPC3, HIF1A, HLF, and MEN1 have been reported in CaPa and other neoplasias as well." (PMID 38397997, 2024). "Application of this technology in HCC remains in its infancy, but a bispecific antibody for GPC3 and the T cell-specific antigen CD3 has been shown to enhance T-cell activation and tumour cell death in HCC cell lines." (PMID 39308986, 2024). "In-depth analyses, including transcriptional profiling and long-term cytotoxicity assays, revealed that sIL-15 significantly contributed to the sustained functional fitness of GPC-3.CAR Vδ1 T cells, promoting durable tumor growth inhibition." (PMID 38338658, 2024). "Immunohistochemistry staining showed the tumor tissues displayed typical HCC features, including the expression of GPC3 and AFP." (PMID 38653754, 2024). "GPC3-CAR-T cells were engineered to express IL-7 and CCL9 for stimulating the proliferation and facilitating migration, which effectively eradicated the tumor." (PMID 39569202, 2024). "CAR-T cells engineered to target both GPC3 and CD147 can selectively kill dual antigen-positive HCC cells, thereby avoiding severe on-target/off-tumor toxicity." (PMID 38679698, 2024). "Normal liver cells and tumor cells clusters were extracted for separate UMAP clustering and further classified by AFP, PTPRC, ALB, GPC3." (PMID 39015573, 2024). "Traditional therapeutic cancer vaccines were typically based on tumor lysates or TAAs such as AFP and GPC3." (PMID 38679698, 2024). "GPC3 CAR-T cells secrete IL15 and IL21, enhancing the proliferation of poorly differentiated GPC3-CAR T cells, maintaining TCF-1 expression, and increasing both the persistence and anti-tumor activity of these cells." (PMID 39136031, 2024). "Immunohistochemically, tumor cells are positive for AE1/AE3, EMA, cytokeratin (CK), brachyury, focally S-100P, MNF116, OSCAR, and glypican 3, as per the study by Rekhi." (PMID 39233954, 2024). "Immunohistochemistry for GPC3 and CK19 was performed on archived tumor tissue and the proportion of positive cells and intensity of staining were recorded." (PMID 39598037, 2024). "Preclinical studies have demonstrated the efficacy of GPC3-targeting CAR-T cells in vitro and in vivo, resulting in effective elimination of GPC3-positive HCC cells, tumor regression, and prolonged survival in mouse models of HCC." (PMID 39417449, 2024). "Oncogenic markers GPC3, HMGA2, and TNFRSF19 are dramatically increased in the tumor section of HBL116." (PMID 39796711, 2024). "GPC3-specific CAR-T cells have demonstrated the capability to eradicate GPC3-positive HCC cells in laboratory settings and GPC3-positive HCC tumor xenografts in murine models." (PMID 39569202, 2024). "Collectively, recent advances in HCC immunotherapy focus on allogeneic GPC-3.CAR Vδ1 T cells expressing sIL-15, demonstrating tumor-specific activation and effective growth control." (PMID 38338658, 2024).
tumor (continued). "This research validated that GPC3 CAR T cells inhibited tumor growth, albeit with varying effectiveness attributed to the different expression of PD-L1 on tumor cells." (PMID 38473878, 2024). "Many are designed to bring immune cells in proximity with tumor cells by targeting both immune markers (CD137/4-1BB, CD27, PD-1, OX-40) and tumor markers (B7-H3, CD47, PD-L1, 5T4, ROR1, claudin, GPC3, HLA-G, PSCA)." (PMID 38254823, 2024). "The spatial transcriptomic analysis unveiled a distinctive pattern in the tumormicroenvironment, where both GPC3 and MUC13 were highly expressed in tumor samplescontrasting sharply with their complete absence in the control sample." (PMID 39872360, 2024). "Higher expression of GLS1 meant the higher expression of AFP, GPC3, Ki67, and VEGFR2; higher T and TNM stages; and higher Edmondson–Steiner grade, which indirectly reflected the relationship between GLS1 and tumour proliferation and invasion ability." (PMID 37946141, 2023). "In the remaining part of this section, we briefly outline the innovative therapeutic approaches utilizing the high expression of GPC3 and AFP to identify tumor cells." (PMID 38173713, 2023). "Treatment with GPC3144‐152 enhanced the infiltration of CD8+ T cells into the tumor environment and their cytotoxicity against TYST tumors in vivo by up‐regulating granzyme B and IFN‐β expression, but down‐regulating GPC3 expression in the tumors." (PMID 37986544, 2023). "Consistent with previous reports, the expression of ACSL4 and GPC3 was increased, and the expression of MT1G and SLC22A1 was decreased in the tumor tissues." (PMID 38188684, 2023). "Although GPC3-CAR-T cells showed anti-tumor activity, the effect was reduced significantly in the presence of GPC3 shed off the tumor cell surfaces." (PMID 37779207, 2023). "Given their ability to stimulate the CTL response, DCs are currently studied for vaccine therapy using specific tumour antigens such as AFP, GPC-3 and MAGEA-1, or total lysate-pulsed." (PMID 37509293, 2023). "GPC-3-targeted CAR-T cells have been proven to have good safety and efficacy in the therapy of HCC, and GPC-3-CAR-T cells with the co-expression of IL-15 and IL-21 demonstrated superior cell proliferation and anti-tumor ability." (PMID 36773210, 2023). "Studies have shown that GPC-3 can be used as an immunotherapy target for HCC, and GPC-3-targeting monoclonal antibodies and GPC-3-targeting chimeric antigen receptor T cells (CAR-T) can effectively kill GPC-3-positive cells, including HCC tumor cells." (PMID 36824129, 2023). "Several tumor markers have been identified for HCC, including alpha-fetoprotein, des-gamma-carboxy prothrombin, and glypican-3." (PMID 38093163, 2023). "As tumor markers that tend to be more highly expressed in HCC cells while lowly expressed in normal hepatic cells, GPC3 and AFP can aid in the direct targeting of tumor cells by cellular therapy modalities, such as monoclonal antibodies and Car-T." (PMID 38173713, 2023). "In this study, the clinical and pathological features closely related to the prognosis of HCC and the expression levels of 13 proteins, including GPC3, CK19, and vimentin, in the tumor tissue were selected for multivariate analysis." (PMID 36973651, 2023). "When the combination scheme of Ep-LMS/Vi-LMS/GPC3-LMS was sequentially applied to capture CTCs in the radical resection group (RR group), it was found that the CTC count was significantly reduced 1 week after hepatectomy, which may be associated with complete removal of the tumor." (PMID 36681851, 2023). "After 30 days of post intratumor injection of anti-GPC3-7 × 19 CAR-T, patients with advanced HCC experienced complete tumor disappearance." (PMID 37371075, 2023). "GPC-3 can significantly promote the proliferation and differentiation of HCC tumor cells and regulate tumor angiogenesis and the immune microenvironment." (PMID 36824129, 2023).
tumor (continued). "Because of the elevated density of peptide-specific cytotoxic T lymphocytes (CTLs) in the TME, HCC patients with high GPC-3 expression in tumor tissues and/or high content of GPC-3 in plasma have a high response rate and a good prognosis for the GPC-3 vaccine." (PMID 36773210, 2023). "IHC staining revealed the tumor cells from the liver metastases were immunoreactive for markers including AFP, GPC-3, and SALL4." (PMID 37781207, 2023). "When incorporated into two TCR-like CARs, (HLA)-A2/GPC3- and HLA-A2/WT1-specific nanobodies selectively recognize and lyse MHC/peptide complex-expressing tumor cells both in vivo and in vitro." (PMID 38067344, 2023). "Tumor cells from patient #4001 were characterized by overexpression of AFP, GPC3, DUSP9, DLK1, GLUL, and AXIN2, a marker of Wnt/β-catenin pathway activation." (PMID 37932266, 2023). "For example, an HSPG glypican-3 (GPC3) is highly expressed in HCC, and an antibody targeting the HS chain of GPC3 was shown to block Wnt signaling and suppress tumor growth in a mouse model of HCC." (PMID 37308486, 2023). "In this study, T cells were genetically engineered into bispecific CAR T cells containing two tumor antigen-binding sites (CD133 and GPC3) and were used to treat patients with double-positive HCC." (PMID 35879685, 2022). "Combination of GPC3 CAR-T cells and PD-L1 CAR-T cells achieved a synergistic anti-tumor effect in vivo." (PMID 35317524, 2022). "Another human anti-GPC3 monoclonal antibody, HS20, that recognizes the HS moiety on the molecule, was shown to block Wnt signaling and inhibit tumor growth." (PMID 35251989, 2022). "ZHX2 suppresses the transcription of oncofetal genes AFP and glypican 3 (GPC3), and works as a tumor suppressor gene in HCC." (PMID 36465389, 2022). "GPC3 and IGF-2 are potential drug targets that have significantly reduced tumour growth and prolonged survival in Phase 1 clinical trials and in animal models respectively." (PMID 36345011, 2022). "Glypican-3 (GPC3) is a heparan sulfate proteoglycan that functions as a Wnt coreceptor, which is one of the key regulators of HCC tumor progression." (PMID 35331259, 2022). "GPC3 provided extensive adhesion for CoG133-CAR T cells, and CD133 provided profound tumor suppression." (PMID 35879685, 2022). "Glypican 3 (GPC3), an oncofetal HSPG anchored to the cell membrane, exhibits elevated expression in tumor cells and tumor vascular cells in HCC, and its expression correlates with a poor prognosis." (PMID 36093115, 2022). "Among the new treatments in ongoing clinical trials, there are also chimeric antigen receptor (CAR) T cells engineered against glypican 3 (GPC3), AFP, and other tumor-specific antigens." (PMID 36551635, 2022). "Another study attempted to compare the induction of the GPC3 T-cell-mediated immune response after radiofrequency ablation (RFA), surgical resection, and TACE in patients with HCC and tumor-bearing mice." (PMID 35884392, 2022). "The expression profiles of genes in the first cluster across all tumours (TOP2A, CDK1, BIRC5, GPC3, IGF2 and AFP) were strongly correlated." (PMID 36345011, 2022). "GPC3 works as a coreceptor for the tumor-regulating WNT protein and can regulate proliferation of (tumor) cells by modulating Wnt, YAP and Hedgehog signalling." (PMID 36289737, 2022). "Ad-IL-12/GPC3 co-immunization promoted the induction and maturation of CD11c+ or CD8+CD11c+ DCs and increased the number of tumor-infiltrating CD8+ T cells." (PMID 36139670, 2022). "Similar to the clinically established tumor markers for HCC AFP and GPC-3, NOPE is highly expressed during fetal liver development but is undetectable in healthy adult hepatocytes." (PMID 35246597, 2022). "GPC3/CD47, a bispecific antibody targeting GPC3 and CD47, was effective in preventing tumor growth through recognition of both antigens." (PMID 35251989, 2022).
tumor (continued). "Tumor markers that contribute to the diagnosis of HCC include AFP heterogeneity, Glypican-3, osteopontin, Des-γ-carboxyprothrombin, Golgi protein-73, abnormal pro-thrombin, and heat shock protein." (PMID 35854221, 2022). "Compared with AFP, the expression rate of GPC-3 in early HCC is significantly higher, especially in patients with tumor diameters of less than 3 cm." (PMID 35624643, 2022). "Over the years, other tumor markers for HCC have been proposed, such as Golgi protein 73 (GP73), Glypican-3 (GPC3), and cytokeratin 19 (CK-19)." (PMID 36119529, 2022). "These CAR-T cells had a much higher proliferation capacity after target cell stimulation than control GPC3-CAR-T cells and showed higher tumor suppression than controls in two HCC tumor xenograft models." (PMID 36291802, 2022). "Compared with CD19 CAR-T cells, monospecific therapy of GPC3 CAR-T cells and PD-L1 CAR-T cells individually inhibited tumor growth in xenografts." (PMID 35317524, 2022). "We examined the stimulation of GPC3-mediated multifunctional CD8+ T lymphocytes in spleen cells and tumor-infiltrating lymphocytes of tumor models immunized with various vaccines." (PMID 36139670, 2022). "GPC3-targeted CAR-T cells are able to destroy GPC3+ HCC cells in vitro and GPC3+ HCC tumor xenografts in mice." (PMID 35251989, 2022). "SF-PL/siGPC3 with selected sizes and zeta potentials, delivered by PEI-modified liposomes, was shown to accumulate at the tumor site and to enter HCC cells, resulting in suppression of both GPC3 and the pro-proliferation gene cyclin D1 expression a." (PMID 35251989, 2022). "CXCL2 is highly expressed in HCC, and engineered overexpression of the CXCR2L receptor (CXCR2) on GPC3-CAR-T cells was shown to enhance CAR-T infiltration and expansion at the tumour site in a xenogeneic HCC model." (PMID 35158772, 2022). "More importantly, Huh7 tumor tissue treated with CoG133-CAR T cells showed a large amount of fluorescence indicating T cell infiltration; in addition, strong positive GPC3 and CD133 fluorescence was simultaneously observed." (PMID 35879685, 2022). "Liver tumour markers, such as AFP, GSTp2, and GPC3, in GKO tumours were reduced in comparison to WT tumours." (PMID 35867177, 2022). "CAR T cell trials targeting other tumor antigens including EpCAM and TGF-β in addition to GPC3 are underway." (PMID 35433430, 2022). "SiRNA-mediated GPC3 silencing in primary HCC cells leads to reduced proliferation, increased apoptosis and impaired tumour cell migration compared to controls." (PMID 35158772, 2022). "GPC3-CAR co-expressing IL-21 and IL-15 have demonstrated superior in vitro and in vivo expansion, persistence and anti-tumour activity." (PMID 35158772, 2022). "In the meantime, we performed T cell proliferation experiments and found that macrophages from the miR-4510 inhibitor primary tumor successfully inhibited CD8+ T cell proliferation in vitro, and overexpression of GPC3 further induced this effect." (PMID 35050429, 2022). "In HCC, antigens such as GPC3, AFP, and MUCIN are often upregulated in addition to some tumor stem cell antigens, which are the targets that CAR-T cells are often designed to attack." (PMID 36291802, 2022). "It was found that the antibody-immunotoxin complex was specifically cytotoxic to GPC3-positive tumor cells, while the 32A9-CAR-T cells destroyed the tumor cells in vitro and promoted regression of HCC xenograft tumors in vivo." (PMID 35251989, 2022). "In summary, the combination of AAV-CC19 and GPC3-targeted CAR-T cell therapy designed in this study effectively increased the migration and infiltration of CAR-T cells into tumor tissues and increased the therapeutic effect of CAR-T cells." (PMID 34527749, 2021). "In clinical trials, GPC3-based monoclonal antibody has shown a certain efficacy in HCC treatment, but it still cannot completely eradicate the tumor." (PMID 34261411, 2021).